IL6 (interleukin 6)
Diseases named in the same sentence as IL6 in open-access papers (continued):
Sharing a sentence is not in itself a finding about the gene and the disease.
infection (continued). "Late infection featured further Th1 reduction, neutrophil accumulation, and NETs activation (H3cit, NE-DNA, MPO), along with reduced CXCL9 but elevated IL-6, IL-21, IL-27, CXCL10, and S100A8 in blood." (PMID 42112327, 2026). "The relative expression of IL-6, IL-10, TNF-α, and IFN-α in the livers of infected mice significantly increased after BVDV infection, indicating that the infection triggers an inflammatory response in the host." (PMID 41514840, 2026). "In the in vivo experiments, the ΔclpB infection group had faster wound healing, reduced tissue damage, and decreased expressions of TNF-α and IL-6 at both protein and mRNA levels." (PMID 41425934, 2025). "Pro-inflammatory cytokines, such as TNF-α, IL-1β, IL-6, and IFN-γ, are critical in initiating inflammatory reactions and serve as primary mediators of immune responses during infection or injury." (PMID 40364844, 2025). "Consistent with prior reports we observed that bone marrow-derived macrophages (BMDMs) infected with L. interrogans serovar Copenhageni strain Fiocruz L1-130 at a multiplicity of infection (MOI) of 100 elicited the secretion of TNF, IL-10, and IL-6." (PMID 40501870, 2025). "The secretion of IFN and proinflammatory cytokines can rapidly recruit intrinsic immune cells to the site of infection and form a “positive feedback” loop under the stimulation of cytokines such as IFN-γ, TNF-α, and IL-6." (PMID 40283905, 2025). "Comparison of serum levels of TNF-α, IL-6, and IFN-γ among patients with different severities of infection." (PMID 40677522, 2025). "It has been shown that IL-6 and TNF-α are signaling components of ADE, and elevated levels of IL-6 in RSV patients indicate a severe infection." (PMID 40557164, 2025). "Four weeks post infection with M.tb HN878, we observed a significant increase in circulating IFN-γ, TNF-α, IL-1β, IL-2, IL-6, IL-12p70, IL-17A/F, IL-15, and IL-33 levels in mice immunized with ID93+EmT4TM compared to saline controls." (PMID 40285479, 2025). "In both lines, pathways associated with the host response to infection, including TNFα signaling via NF-κB, IL6/JAK/STAT3 signaling, and apoptosis, were significantly upregulated within 4 hours post-infection and remained elevated at 24 hours." (PMID 40766562, 2025). "It has been reported that ORF7b functions in suppressing IFN-interferon production during early infection to facilitate evasion of host detection and induction of cell apoptosis by promoting the expression of TNF-α and IL-6." (PMID 40668819, 2025). "To validate this up-regulation, we quantified the expression of IL6, GBP1, GBP2 and ISG15 in the same infection condition as bulk RNA-seq by qPCR." (PMID 39777915, 2025). "Cytokine profiling of macrophages post-infection revealed that CB1R-KO mice had reduced IL-10 levels, along with increased IL-6 and TGF-β, suggesting a dysregulated polarization state that combines pro-inflammatory and regulatory elements." (PMID 40161677, 2025). "There was robust upregulation of proinflammatory cytokine genes (TNF–α, IL–1β, and IL–6) and chemokine genes (RANTES, MIP–1α, and MIP–1β), reflecting a strong inflammatory response that recruits immune cells to the site of infection." (PMID 41214723, 2025). "The relative mRNA levels of inflammatory factors were also increased after infection, including Interferon-γ (IFN-γ), Transforming growth factor-β1 (TGF-β1), Interleukin-4 (IL-4), and Interleukin-6 (IL-6)." (PMID 39927263, 2025). "Concurrently, gaseous irritants such as NO2 and O3 disrupt epithelial barrier integrity and trigger excessive release of pro-inflammatory cytokines (e.g. IL-6, TNF-α), priming the lungs for exaggerated inflammatory responses upon infection." (PMID 40688748, 2025). "Using a murine ‘two-hit model’ combining CLP with secondary infection of P. aeruginosa, we observed immunosuppressive manifestations, such as reduced TNF-α and IL-6 secretion, elevated bacterial load, and increased mortality upon secondary insult." (PMID 41082631, 2025).
infection (continued). "In GPA-MARV-challenged animals, the proinflammatory cytokines IFN-α, IL-6, IL-8, IP-10 and MCP-1 all increased following infection, with levels peaking in most animals at the time of euthanasia." (PMID 40921747, 2025). "The infection also compromised blood–brain barrier (BBB) permeability, allowing peripheral inflammatory markers such as IL-6 and TNF-a to enter the brain." (PMID 39860337, 2025). "The results of ELISA showed that PECP was able to significantly inhibit the elevation of cytokines TNF‐α, IFN‐γ, and IL‐6 and chemokines IP‐10, MCP‐1, and MIP‐1α after infection in mice." (PMID 40757669, 2025). "Supporting these findings, elevated serum cytokines such as TNF-α, IL-6, MCP-1, and MIP-1α confirmed that PMSS infection triggers a more robust inflammatory response than SS." (PMID 41183799, 2025). "The levels of IL-6, IL-10, and IFN-γ increased after infection, peaked at various time points, and then declined by 21 dpi." (PMID 41295722, 2025). "Previous studies have confirmed that IL-6 and IL-1 stimulate hepcidin transcription through STAT3 signaling during infection and inflammation." (PMID 40298788, 2025). "The data indicated that IL-1β, IL-6, IL-8, IL-18, TNF-α, and COX-2 mRNA levels in the spleen in the infection group were significantly upregulated (p < 0.001)." (PMID 40427533, 2025). "The ELISA results revealed that EPEC66 infection significantly increased the levels of the pro-inflammatory cytokines TNF-α, IL-1β, and IL-6 in the ileum, compared with those in the NC group (p < 0.01)." (PMID 41373958, 2025). "Immunofluorescence results demonstrated that β-acids accelerated wound healing by markedly reducing IL-6 and TNF-α, increasing VEGF levels, and suppressing infection." (PMID 41415825, 2025). "The experiment revealed that on the 10th day post-infection, the LNP-Opt-mRNAMOMP group displayed markedly lower lung concentrations of IFN-γ and IL-6 in comparison to the PBS group." (PMID 41190885, 2025). "While IL-1β, IL-6, and TNF-α levels were similar at admission, IL-1β and TNF-α significantly increased during follow-up, indicating immune activation in later infection stages." (PMID 40611327, 2025). "Both IL-6 and TNF-α are key signaling molecules released during macrophage activation; elevated concentrations indicate an inflammatory response triggered by infection detection." (PMID 41403880, 2025). "Cytokines, such as interleukins (e.g., IL-6) and tumor necrosis factor-alpha (TNF-α), play a dual role during infection." (PMID 40227362, 2025). "To further investigate the antiviral mechanism of AVI-4206, we measured the abundance of the antiviral cytokines IP-10, IL-2, IL-6, and TNF-α in lung tissue at 4 and 7 days post-infection." (PMID 39149230, 2025). "For example, miR-146a plays an anti-infection role in THP-1 cells by negatively regulating secretion of TNF-α and IL-6." (PMID 40597229, 2025). "SOR pretreatment also resulted in reduced levels of the inflammatory markers IL-6 and TNF-α in the BALF at 6 days post infection." (PMID 40858544, 2025). "The immune response to infection triggers the release of pro-inflammatory cytokines, such as tumor necrosis factor-alpha (TNF-α), interleukin-1β (IL-1β), and interleukin-6 (IL-6), leading to widespread tissue damage, capillary leakage, and hypoperfusion." (PMID 40429550, 2025). "SGE-enhanced dissemination of virus to joint tissues resulted in higher upregulation of key arthritogenic cytokine transcripts, including TNF-alpha and IL-6, and the chemokines CXCL2, CCL2, and CXCL10 at day 7 post infection." (PMID 41362756, 2025). "Analysis of the pulmonary transcriptional levels of Monocyte chemoattractant protein-1 (MCP-1), IL-6, and TNF-α revealed that their expression was highest at 12 hpi following infection with both the HY037 and HY041T strains." (PMID 41274864, 2025). "After drainage, HMGB1, IL-1, IL-6, and TNF-α in the bile of AOSC patients were reduced as infection decreased." (PMID 40054422, 2025).
infection (continued). "Infection with IAV leads to a distinct immune response in the lungs, production of pro-inflammatory cytokines and chemokines (IL-1b, IL-6, G-CSF, KC, MIP-1b), and decreased bronchodilation." (PMID 41567998, 2025). "IL6 and IL8 showed significant changes at 4 h post-infection (p-value = 0.0417 and p-value = 0.0115, respectively), while MCP1 and SOCS3 exhibited changes from 1 and 2 h post-infection, respectively (p-value < 0.05)." (PMID 40141288, 2025). "Specifically, estradiol alleviates virus-induced immunopathology by downregulating the expression of pro-inflammatory cytokines such as TNF-α, IL-6, and CCL2, thereby mitigating excessive pulmonary inflammation and improving infection outcomes." (PMID 40872527, 2025). "IL-6 and MIF are typically elevated during infection and contribute to inflammation, but our findings suggest that their reduction does not impair parasite control in BeWo cells." (PMID 41415569, 2025). "Offspring of HFD-fed dams exhibited significantly blunted cytokine and chemokine responses during infection, including reduced levels of serum GM-CSF, TNF-α, IL-1β, IL-6, IL-10, and MCP-1 and peritoneal G-CSF, IL-6, and MCP-1." (PMID 40766470, 2025). "We quantified serum levels of IL-4, IL-6, IL-8/CXCL-8, IL-27, CCL-2, CXCL-9, CXCL-10, and IgG using Luminex and ELISA assays during the acute and subacute phases of infection." (PMID 40711072, 2025). "This preceded the transcriptional upregulation of inflammatory cytokines, including IL-1β, IL-6, IL-18, and TNF-α, which only became prominent at 12-24 hours post-infection." (PMID 41281739, 2025). "Together, these data show that different strains lead to different signatures of inflammatory responses in vivo, but that relative induction of MCP-1, IL-6, IL-10 and IFN-γ correlates with degree of virulence in a murine infection model." (PMID 40587585, 2025). "In contrast, H37Rv infection significantly upregulated IL18, whereas downregulating IL6, both of which are prominent proinflammatory cytokines." (PMID 40738187, 2025). "Upon infection of PBMCs, HIV-1ADA induced significantly higher levels of pro-inflammatory cytokines IL-1α, IL-1β, IL-6 and TNF-α as measured via Luminex assay." (PMID 40313367, 2025). "By day 10 post-infection, infected mice exhibited significantly elevated levels of MCP-1, IFN-γ, IL-12 p70, TNF-α, IL-6, and IL-10 in the brain, indicating a strong inflammatory response." (PMID 40078875, 2025). "Synthesized primarily by hepatocytes in response to interleukin-6 and other pro-inflammatory cytokines, CRP levels can rise rapidly within hours of infection or tissue injury, often reaching peak concentrations within 48 h." (PMID 40647525, 2025). "At three months post infection, hospitalized patients exhibited elevated levels of ICAM-1, VCAM-1, and IL-6, alongside a detectable immunoreactivity in SARS-CoV-2-specific T-cell response." (PMID 41226453, 2025). "At different time points post infection, the mRNA level of the cytokines TNF-α, IL-8, and IL-6 were monitored by RT-qPCR." (PMID 40253364, 2025). "The expression of TNF-α, IL-1β, IL-6, IL-10, TGF-β, and hepcidin mRNA in WT increased sharply and reached a peak on day 1 post-infection with A. hydrophila, followed by a decrease." (PMID 40298788, 2025). "Regarding biomarkers of infection, both groups had similar levels of C-reactive protein (CRP), IL-6 and procalcitonin, which suggested that the severity of COVID-19 infection were similar between groups." (PMID 39911872, 2025). "IL-1β was produced by M2-like macrophages, dendritic cells, and neutrophils, whereas M1-like macrophages, which differentiated post-infection, produced IL-23, TNF-α, and IL-6, acting as initiators and amplifiers of the cytokine storm." (PMID 40127923, 2025). "We observed that nine biomarkers (fractalkine, IFNγ, IL-5, IL-6, IL-10, IL-12, IL-13, IL-21, and TNFα) had significantly increased levels post-infection with subtype C HIV-1 compared to the pre-infection levels." (PMID 40862133, 2025).
infection (continued). "such as interleukin-6 (IL-6) and tumor necrosis factor-alpha (TNF-α), are essential in the initial response to infection, injury, or exercise." (PMID 40402402, 2025). "Consistent with the cell infection assay results, K247Q demonstrated the highest levels of proinflammatory cytokines TNF-α, IL-6, and IL-1β, particularly when compared to those produced by K247R at 24 h.p.i." (PMID 40167330, 2025). "In response to in vitro infection, monocytes secrete type I interferons (IFNs), tumor necrosis factor-α (TNF-α), granulocyte colony-stimulating factor (G-CSF), and IL-6, enabling the activation and recruitment of innate and adaptive immune cells." (PMID 41280933, 2025). "This study demonstrated that Presepsin and IL-6 are more reliable than CRP and PCT for the early detection of postoperative infections in HTx patients." (PMID 40806991, 2025). "Complementary ELISA data demonstrated a significant augmentation in the secretion of cytokines IFN-γ, IL-4, IL-6, IL-17A, TGF-β, GATA-3, T-bet, IL-10, and TNF-α in the Pm_OMVs-infected group relative to the Pm group at 24 hours post-infection (P < 0.01)." (PMID 41306977, 2025). "Post-infection, CF7066 significantly upregulated the transcriptional expression of inflammatory factors such as CCL4, IL-6, IL-8, and TNF-α, exhibiting the highest mRNA levels." (PMID 40793820, 2025). "In murine models, RSV mono-infection induced minimal TNF-α and IL-6 levels, whereas IAV mono-infection significantly elevated these cytokines." (PMID 40005506, 2025). "Ahsg (also termed fetuin-A) belongs to the ‘acute phase proteins’ (APPs), and its expression is negatively regulated by several pro-inflammatory cytokines such as TNF, IL-1, IL-6 and IFN-γ during infection or other inflammatory illnesses." (PMID 41009783, 2025). "After infection of mice with the HY/HA-ΔL226/R229I strain, levels of TNF-α decreased at 3 dpi, while IL-6 and IL-1β levels increased at 5 dpi." (PMID 40338080, 2025). "Following infection, a reproducible antiviral cytokine response, including a consistent increase in CXCL10, IL-6, IFN-λ1, IFN-λ2/3, and IFN-β, was detected across all models." (PMID 39981254, 2025). "Following the infection of RAW264.7 cells with SFTSV at the MOI of 200 for 24 or 48 h, the levels of IL-1β, IL-6, IL-10, TNF-α, and MCP-1 were measured by using qPCR." (PMID 41472750, 2025). "During infection, there was a notable increase in the production and release of pro-inflammatory cytokines, including IL-8, TNF-α, and IL-6." (PMID 40101060, 2025). "Infection with 103 TCID50 of PRV-GXLB-2013 resulted in significantly elevated levels of TNF-α, IL-1β, IL-6, IL-8, and MLKL in brain tissues, serum, and C8-D1A cells, compared to the control group (p < 0.01)." (PMID 40732040, 2025). "Pro-inflammatory factors, such as IL-1β, IL-6, and TNF-α, can mediate host’s inflammatory response by rapidly generating an immune response after pathogen infection." (PMID 40821810, 2025). "Interleukin 6 (IL-6) and procalcitonin (PCT), as common important indicators reflecting the degree of inflammation, will increase significantly when the body has infection and increase with the progression of MPP." (PMID 40469159, 2025). "Our findings demonstrate that primary monocytes and related THP-1 cells are permissive to abortive infection by RSV, leading to increased expression of proinflammatory cytokines and chemokines, including IP-10, IL-6, and CCL2." (PMID 41280933, 2025). "LINC02528+/– macrophages exhibited significantly upregulated transcriptional and translational levels of IL-1β upon H37Rv infection, while exerting minimal impact on TNF-α and IL-6 expression." (PMID 41433368, 2025). "Infection markers such as erythrocyte sedimentation rate (ESR), high-sensitivity C-reactive protein (CRP), calcitonin, interleukin-6 (IL-6), and ferritin were elevated." (PMID 41341819, 2025).
infection (continued). "Results showed elevated levels of pro-inflammatory cytokines such as TNF-α, IL-6, IL-1β, and chemokines CCL5 (RANTES), and IP-10 (CXCL10) after infection with rHPh-TX H5N1." (PMID 40712003, 2025). "Like PMs, THP-1 cells also produced IL-6, CCL4, CCL2, IL-1RA, CCL3, and CXCL9 upon infection with the RSV strain A-0594, although the peak of these responses differed in some cases." (PMID 41280933, 2025). "Astrocytes, in turn, respond to these signals by releasing their own cytokines and chemokines, such as interleukin-6 (IL-6) and CCL2, further amplifying the inflammatory response and attracting more immune cells to the site of injury or infection." (PMID 41466978, 2025). "Risk factors for the development of fibrosis include the severity of initial lung injury, elevated inflammatory markers such as interleukin-6 (IL-6) and lactate dehydrogenase (LDH), and low albumin levels during the acute phase of infection." (PMID 41552096, 2025). "Levamisole significantly inhibited IL-1β, IL-6, IL-8, IL-18, TNF-α, and COX-2 mRNA expressions in the spleen compared to the infection group (p < 0.001)." (PMID 40427533, 2025). "Sequential infections revealed that prior RSV infection decreased TNF-α and IL-6 levels following subsequent IAV infection, suggesting protective effects mediated by innate immune responses." (PMID 40005506, 2025). "IL-6-induced STAT3 signaling upregulates hepcidin expression, sequestering iron to limit its availability to pathogens during infections while enhancing immune responses by promoting production of inflammatory mediators and acute-phase reactants." (PMID 41007630, 2025). "Pro-inflammatory cytokines are released by infection, including TNF-α, IL-6, and IL-18, mediating inflammation and clinical symptoms." (PMID 40034419, 2025). "While markers such as C-reactive protein (CRP) and interleukin-6 (IL-6) have been extensively studied in relation to the atherosclerotic process, procalcitonin (PCT), a known marker of infection, has recently garnered attention in this context." (PMID 40963340, 2025). "The expression of IL-1β, IFN-α2, IFN-γ, TNF-α, MCP-1 (CCL2), IL-6, IL-8 (CXCL8), IL-10, IL-12p70, IL-17A, IL-18, IL-23, and IL-33 was assessed in apical washes at different time points after infection using a 13-plex immunoassay." (PMID 40143308, 2025). "In lung tissue, IL1B, IL6, IL10, CXCL2, CCL3 and CCL5 levels also rose in both genotypes following infection, although these markers were significantly lower in TLR7 KO mice." (PMID 40442368, 2025). "Quantitative PCR analysis revealed increased mRNA levels of proinflammatory cytokines and chemokines (Tnf, Il6, Il1b, Ccl2, Cxcl1, and Cccl2) in SARS-CoV-2-infected lungs compared with those in naïve lungs on days 2 and 5 post-infection." (PMID 40162785, 2025). "Following infection, macrophages of both sexes showed similar increases in TLR7 and IFNB expression, while significant upregulation of IL6 and TNFA was evident only in male macrophages." (PMID 40143355, 2025). "In the context of primary HPV infection or high infection rates, magnesium enhances immunologic synapse efficacy by activating the LFA-1 protein on T cells and modulates inflammatory factors (IL-6), indirectly supporting antiviral immunity." (PMID 40521368, 2025). "It has been demonstrated that there is a positive correlation between serum IL-6 expression and an increase in the inflammatory response, which may effectively respond to the level of inflammation within the body and plays a crucial role in determining infection prognosis and severity." (PMID 40150581, 2025). "As expected, C. albicans induced higher levels of G-CSF, IL-6, IL-1α, and IL-1β than N. glabratus cells in an in vitro OEC infection model." (PMID 40233931, 2025).